TLR2 (toll like receptor 2)
Diseases named in the same sentence as TLR2 in open-access papers (continued):
Sharing a sentence is not in itself a finding about the gene and the disease.
atherosclerosis (continued). "Several reports have documented that TLR2 and TLR4 signaling pathways could induce vascular inflammation and insulin resistance, leading to a higher risk of atherosclerosis." (PMID 35872802, 2022). "Taken together, C. pneumoniae infection may promote VSMC migration and atherosclerosis development by increasing the level of mtROS through TLR2 to activate the JunB-Fra-1/MMP2 signaling pathway." (PMID 35493076, 2022). "TLR2 has also been shown to have an important role in atherosclerosis." (PMID 35493076, 2022). "In atherosclerosis, lipoproteins trigger TLR2 and TLR4 signalling pathways." (PMID 35017526, 2022). "Regardless, our findings suggest that chronic exposure to microbiota-related glycine lipids, such as L654, may dampen inflammation-related pathways via TLR2 and prevent atherosclerosis progression and liver injury." (PMID 35278409, 2022). "TLR2 is recognized as an important factor in atherosclerosis and calcification." (PMID 34749728, 2021). "TLR2/Myd88 signaling pathway plays an important role in the pathogenesis of atherosclerosis." (PMID 34901005, 2021). "TLR2 signaling has also been demonstrated to be involved in the development of atherosclerosis." (PMID 32378144, 2021). "Activation of the endothelial innate immune pathways of TLR2 and TLR4 is known to modulate pathways involved in endothelial permeability and coagulation that are associated with the initiation and progress of atherosclerosis, as well as with acute atherothrombotic adverse events." (PMID 34944024, 2021). "As TLR2 plays a pathological role in trigging atherosclerosis and vascular calcification, we thus determined whether TLR2 influences 5-MTP production, we analyzed vascular 5-MTP by IHC in ApoE−/−Tlr2−/− double knockout mice." (PMID 34749728, 2021). "In addition, blocking the TLR2 signaling pathway can reduce the inflammation-promoting pathway in human atherosclerosis." (PMID 32002588, 2020). "However, as we observed the strongest and consistent response with the TLR2-Agonist PAM3cys4 and considering the importance of vascular wall TLR2 in atherosclerosis formation, we performed subsequent experiments using the TLR2-agonist PAM3cys4." (PMID 30728822, 2019). "In addition, atherosclerosis was ameliorated in TLR2 knockout mice, suggesting that TLR2 plays a critical role in the progression of vascular inflammation." (PMID 31023999, 2019). "TLR2 and TLR4, subfamilies of TLRs, expressed in lesions, macrophages, dendritic cells, endothelial cells, and vascular smooth muscle cells, have been implicated in the pathogenesis of atherosclerosis." (PMID 30671470, 2018). "In contrast to the effect of TLR2-deficiency on P. gingivalis-induced atherosclerosis, we demonstrate that TLR4-deficiency leads to increased disease severity, indicating a protective role for TLR4 signaling in P. gingivalis-induced atherosclerosis." (PMID 28348558, 2017). "TLR2 is known to be overexpressed in macrophages after LPS recognition and in pro-inflammatory conditions, acting as a key player in inflammation and atherosclerosis progression." (PMID 29166412, 2017). "The role of TLR2 in atherosclerosis has been reinforced by other studies." (PMID 27795867, 2016). "In TLR2−/− and TLR4−/− mice, atherosclerosis-associated inflammation was diminished." (PMID 27795867, 2016). "We hypothesize that up-regulation of TLR2 by intermittent hypoxia may lead to systemic inflammation, insulin resistance and atherosclerosis in patients with obstructive sleep apnea." (PMID 26657991, 2015). "It has been suggested that endogenous TLR-2 agonists may have an impact on atherosclerotic disease progression by the fact that TLR-2 knock out mice exhibit a decreased severity of experimentally induced atherosclerosis." (PMID 24498948, 2013).
atherosclerosis (continued). "While Type 1 diabetes (T1D) promotes the development and progression of atherosclerosis, the effect of T1D on TLR2/4-mediated inflammatory responses in coronary artery endothelial cells (CAECs) remains unclear." (PMID 21162749, 2010). "Indeed, deletion of either TLR-2 or TLR-4 confers a similar degree of protection from lesion development in murine models of atherosclerosis." (PMID 20652007, 2010). "Differences in expression of TLR2 could result either from differences between early versus late disease stage, or a difference between murine and human atherosclerosis." (PMID 20652007, 2010). "Genetic deficiency of TLR2 reduces diet- and/or pathogen-associated atherosclerosis in ApoE+/− mice, along with differences in plaque composition suggesting greater structural stability while TLR-2 ligand-specific activation triggers atherosclerosis." (PMID 18787704, 2008). "Therefore, in the work reported here, we examined the effect of genetic deletion of TLR2 on the progression of atherosclerosis driven by a high fat diet and/or P. g infection in the ApoE+/− murine model." (PMID 18787704, 2008). "Other pathogens studied inrelation to atherosclerosis are Bacteroidesforsynthus, where the protein A secreted by the bacterium acts through CD14and TLR2 ligations to induce atherosclerosis, whereas in the case of Streptococcus mutans it is the proteinAgI/II that acts through CD14 and TLR4." (PMID 18551190, 2008). "Mechanistically, DHL effectively alleviates atherosclerosis by promoting cholesterol efflux and inhibiting inflammation through the TLR2/PPAR-γ/NF-κB signaling pathway, which suggests that DHL may serve as a new treatment strategy for atherosclerosis (As seen in Graphic abstract)." (PMID 40537740, 2025). "In addition to attenuating these inflammatory diseases, Sj-Cys attenuated metabolic diseases and atherosclerosis like atherosclerotic renal damage through promoting Treg and M2 macrophage polarization, mediated by inhibiting the Toll-like receptor 2 (TLR2)/MYD88 signaling pathway." (PMID 39314046, 2024). "Additionally, we proved that TLR2 co-expressed genes are enriched in the gene group of atherosclerosis and atherosclerotic cardiovascular disease, further suggesting that TLR2 may play a vital part in the progress of coronary atherosclerosis to MI." (PMID 35840880, 2022). "Signalling caused by PAMPs or their derivatives formed during processing may stimulate innate Toll-like receptors (TLR2 and TLR4), leading to strong immune reactions associated with inflammation, type 2 diabetes, atherosclerosis, and increased cardiometabolic risk factors." (PMID 34836203, 2021). "Interestingly, deficiency of TLR2 in myeloid cells had no influence in the development of atherosclerosis, suggesting the role of endothelial TLR2 in atherogenesis." (PMID 33062141, 2020). "Although atherosclerosis induced by a high-fat diet might not identical to vascular inflammation induced by TLR2, atherosclerosis might be available as a model of TLR2-mediated vascular inflammation because of the strong relationship between TLR2 and atherosclerosis." (PMID 31023999, 2019). "Thus, the current study suggests that hypoxic induction of TLR2 could be one of the mechanisms leading to systemic inflammation, atherosclerosis and insulin resistance in OSA." (PMID 26657991, 2015). "Studies controversial showed that alterations polymorphic in TLR-2/4 receptor may or may not associate itself with in atherosclerosis and in CHD." (PMID 25329057, 2014).
atherosclerosis (continued). "Thus it may be speculated that increased vesl-2 protein in ApoE+/−-TLR2+/+ mice fed a high fat diet and injected with P. g may lead to an increase in intracellular calcium, contributing to the increased atherosclerosis in this group of mice." (PMID 18787704, 2008). "The potential role of TLRs, including TLR2 and TLR4, in the pathogenesis of atherosclerosis and inflammatory effects of Ox-LDL has been reported." (PMID 39404395, 2024). "Toll-like receptor 2 (TLR2), a functional inflammation-related receptor, promotes the formation of atherosclerosis." (PMID 39252788, 2024). "The expression of TLR2 and TLR4 at the wall of the blood vessel can enhance atherosclerosis in a synergistic way." (PMID 37520489, 2023). "In turn, it has been reported that activation of some TLRs such as TLR2 and TLR4, leads to the transcription of adhesion molecules such as VCAM and ICAM in a process mediated by NF-κB, facilitating atherosclerosis progression." (PMID 37175608, 2023). "The expression of TLR2 and TLR4 at the blood vessel wall can enhance atherosclerosis in a synergistic way." (PMID 35928361, 2022). "In this study, it was shown with DO analysis that TLR2-positive-related genes were mainly enriched in arteriosclerosis, arteriosclerotic cardiovascular disease, and atherosclerosis, indicating that TLR2 may be involved in the development of atherosclerosis into MI." (PMID 35840880, 2022). "Coronavirus disease-COVID-19 and lipid and atherosclerosis connect with TRAF3, TLR2, SELP and CASP1 deregulated molecules." (PMID 36553678, 2022). "Bioinformatic and correlation analyses of differentially expressed immune cells helped to identify CCL4, TLR2, IL1B, and PTPRC as hub genes in atherosclerosis formation and plaque progression." (PMID 35509837, 2022). "Based on the correlation criteria and correlation criteria value, CCL2, CCL4, TLR2, IL1B and PTPRC were identified as hub immune genes in atherosclerosis." (PMID 35509837, 2022). "Cigarette smoke significantly enhanced the expression of TLR2/TLR4 mRNA in histamine and lipopolysaccharide (LPS) treated cells, which suggested that upregulation of TLR2/TLR4 signaling promoted progression of atherosclerosis." (PMID 33995400, 2021). "5-MTP administration reduced chondrogenesis and calcification in HFD-induced atherosclerosis in ApoE−/− mice and inhibited VSMC phenotypic switch to calcified chondrocytes induced by TLR2 and TLR4 activation." (PMID 34749728, 2021). "Quercetin, which is a green tea flavonoid, inhibited the expression of TLR2 and TLR4 and nuclear translocation of the NF-κB p65 subunit in atherosclerosis rats." (PMID 34943034, 2021). "The expression levels of TLR1, TLR2, and TLR4 were found elevated in human and experimental models of atherosclerosis." (PMID 31565149, 2019). "TLR2 was shown to trigger low-grade chronic inflammation and activation of macrophages, present in obesity, T2DM, or atherosclerosis, and a higher TLR2 expression was shown in monocytes of T2DM patients compared with control subjects." (PMID 30983877, 2019). "Other studies showed that TLR2 expression is increased in patients with diabetes, and TLR2/TLR4 stimulation induces an enhanced inflammation in obese patients with atherosclerosis." (PMID 31582899, 2019). "HSP60 stimulates the host macrophages during processes such as atherosclerosis, and is mostly involved in the TLR4 pathway, although it can also play a role in the TLR2 pathway." (PMID 31086403, 2019). "VB-201, an oxidized phospholipid mimic which is orally available, binds to TLR2 and CD14 to limit downstream inflammatory pathways and has beneficial effects on atherosclerosis and experimental autoimmune encephalomyelitis." (PMID 29515999, 2018). "Our work has focused on defining the role of TLR2 and TLR4 signaling in P. gingivalis-mediated inflammatory atherosclerosis using a well-defined hyperlipidemic mouse model (ApoE−/−)." (PMID 28348558, 2017).
atherosclerosis (continued). "Different from endolysosomal TLRs, cell surface TLRs such as TLR2 and TLR4 have been proven detrimental in atherosclerosis from most tested experimental models." (PMID 28405010, 2017). "This review outlines the pathophysiological role of TLR2, TLR4, and TLR9 in atherosclerosis, focusing on evidence from animal models of the disease." (PMID 27795867, 2016). "For instance, TLR2 and TLR4 participate in the pathogenesis of atherosclerosis, autoimmune colitis, systemic lupus erythematosus (SLE), diabetes and Alzheimer’s disease." (PMID 26987407, 2016). "The subsequent sections of this review focus on the roles of TLR2, TLR4, and TLR9 in the pathogenesis of atherosclerosis." (PMID 27795867, 2016). "Most studies hitherto have focused on the implications of TLR4 or TLR2 on atherosclerosis, while the data on the roles of TLR9 in atherosclerosis is scarce." (PMID 26257462, 2015). "Pg injection herein significantly increased local aortic expressions of TLR-2 and TLR-4, indicating that Pg stimulated systemic inflammatory immune response through TLR-2 and TLR-4, finally leading to atherosclerosis." (PMID 26063970, 2015). "Studies in animal models showed that both receptors, TLR-2 and TLR-4, are related to atherosclerosis, insulin resistance and diabetes, features present in the MetS." (PMID 25329057, 2014). "TLR2/TLR1 specific small molecule inhibitors have been recently identified and will be worth screening in animal models of AMD, angiogenesis, and atherosclerosis." (PMID 25184331, 2014). "The vital function of TLR2, 4-mediated signaling pathway in VSMC activation and atherosclerosis formation has been confirmed, whereas the role of NODs in these field remain to be elucidated." (PMID 22997500, 2012). "Human and mouse atherosclerosis is characterised by an increased expression of TLR1, TLR2 and TLR4 (and to some extent TLR5), mainly by macrophages and endothelial cells." (PMID 21526997, 2011). "There has been shown to be co-localisation of p65 (an NFκB family member) with both TLR2 and TLR4 in macrophages in atherosclerosis." (PMID 21526997, 2011). "Although the expression of these genes was not quantified in the study, TLR2, IFN-γ, and iNOS have previously been implicated in atherosclerosis and myocardial inflammation in both humans and animal models." (PMID 40076974, 2025). "While in TLR-2 and LDL-R-deficient mice, angiotensin II infusion resulted in AAA formation but not atherosclerosis, both were attenuated in mice deficient in TLR-4 and LDL-R." (PMID 37508529, 2023). "In addition, CCL4, TLR2, IL1B and PTPRC were considered to be immune marker genes in atherosclerosis development." (PMID 35509837, 2022). "They showed that TLR2 expression on vascular endothelium, i.e., on non-bone marrow derived cells, at sites of nonlaminar flow contributes to the atherosclerosis." (PMID 30225265, 2018). "This experiment showed that TLR2 expression on non-bone marrow derived cells, such as vascular endothelium, at sites of nonlaminar flow contributes to the atherosclerosis." (PMID 27795867, 2016). "Furthermore, other common pathognomonic factors such as the Toll-like receptors (TLR2 and TLR4) play key roles in atherosclerosis." (PMID 26339139, 2015). "We hypothesize that CS enhances histamine-mediated upregulation of TLR2/TLR4 signaling in the endothelium and promotes progression of atherosclerosis." (PMID 26617606, 2015). "Additionally, a previous study documented that common mechanisms of signaling via TLR2, TLR4 and MyD88 link stimulation by multiple pathogens and endogenous ligands to atherosclerosis progression." (PMID 25010102, 2014).
atherosclerosis (continued). "Many of the genes differentially regulated during monocyte-to-macrophage differentiation (downregulated genes include JAK2, STAT6, TLR8, and TLR2, and upregulated genes include VEGFB, TGFB1, FN1, IL-1R2, SCARB1, MSR1, and CD163) have been previously reported in the pathogenesis of atherosclerosis." (PMID 25011540, 2014). "The role of TLR2 and TLR4 has been extensively studied in models of atherosclerosis." (PMID 21526997, 2011). "Interestingly, transfection of both TLR2 and TLR4 together resulted in a synergistic acceleration of atherosclerosis." (PMID 21526997, 2011). "Moreover, specific antibodies could facilitate inflammation via activating the TLR2/CD14 receptor complex, which contributes to atherosclerosis-related complications." (PMID 40458459, 2025). "Furthermore, TLR2 can induce chondrogenesis in vascular smooth muscle cells through osteoprotegerin and IL-6-mediated RANKL, leading to vascular calcification and thus promoting atherosclerosis formation." (PMID 35509837, 2022). "TLR2 is involved in the early atherosclerosis in mice, and could enhance atherosclerosis via targeting the cells originate from non-bone marrow." (PMID 34688276, 2021). "Employing hyperlipidemic ApoE−/− mice and ApoE−/− mice lacking TLR2, it was observed that those lacking TLR2 failed to accelerate atherosclerosis in response to P. gingivalis, supporting that TLR2 is necessary for the infection-accelerated atherosclerosis phenotype." (PMID 29621153, 2018). "Histologic evaluation of vascular tissue in experimental animals identified enhanced TLR2 and TLR4 expression in aortic arch tissue of infected mice compared with uninfected supporting a potential involvement of TLRs in P. gingivalis accelerated atherosclerosis." (PMID 29621153, 2018). "In the current study we demonstrated that although M. oryzae does not activate TLR4 signalling (due to non-detectable levels of LPS) and stimulates only mild TLR2 signalling, this bacterium can trigger an aggressive macrophage-mediated pro-inflammatory response that may potentiate atherosclerosis." (PMID 24874661, 2014). "A deficiency in either TLR6 or TLR1 did not reduce atherosclerosis disease induced by exposure to a high fat diet, all together suggesting that TLR6 and TLR1 individually may not be sufficient per se, but will act together with TLR2 as heterodimers." (PMID 23880853, 2013). "Our results indicate that the activation of CD14, TLR4, and TLR2 on monocytes and macrophages by a very early form of oxidized LDL induces the secretion of pro-inflammatory cytokines such as IL-1β and IL-6, which may contribute to or exacerbate inflammatory responses during atherosclerosis." (PMID 20946675, 2010). "Conversely, the expression of TLR2 and TLR4 on monocytes (both increased during the development of atherosclerosis) was reduced in the patient’s non-classical monocyte fractions; however, this has been reported before in patients with chronic inflammation." (PMID 40149441, 2025). "Indeed, we have recently demonstrated that a TLR-2 blockade can inhibit cytokine, chemokine and MMP production in human atherosclerosis, while interruption of TLR-4 signalling did not have a significant impact on the production of proatherogenic mediators." (PMID 20652007, 2010).